MFF (mitochondrial fission factor)
Diseases named in the same sentence as MFF in open-access papers (continued):
Sharing a sentence is not in itself a finding about the gene and the disease.
mucinous ovarian cancer (1 paper, 2023). An invasive malignant neoplasm that arises from the ovary and is characterized by the presence of malignant epithelial cells that contain intracytoplasmic mucin and may resemble the epithelial cells of the endocervix or gastrointestinal tract. "Meanwhile, the results also showed that, similar to CPT1A, MFF had a higher IHC score for protein expression in endometrioid and mucinous ovarian cancers." (PMID 37291333, 2023).
multiple myeloma (1 paper, 2023). "In a recent proteomic study, we identified the key mitochondrial fission factor, MFF, as a new interacting protein of TRAF3, a known tumor suppressor of multiple myeloma and other B cell malignancies." (PMID 36776285, 2023).
Myalgia (1 paper, 2017). "Although mitochondrial genes did not figure prominently among our DEGs, individual mitochondrial genes, including mitochondrial fission factor (MFF) and uncoupling protein-3 (UCP3) exhibited markedly altered expression in muscle of patients with statin-associated myalgia." (PMID 28771594, 2017).
non-small cell lung carcinoma (1 paper, 2023). A group of at least three distinct histological types of lung cancer, including non-small cell squamous cell carcinoma, adenocarcinoma, and large cell carcinoma. "In 72 non-small cell lung cancer (NSCLC) cases, overexpressed MFF formed complex with the key regulator of mitochondrial OMM permeability VDAC1 to regulate cell apoptosis." (PMID 36647167, 2023).
osteosarcoma (1 paper, 2015). A usually aggressive malignant bone-forming mesenchymal neoplasm, predominantly affecting adolescents and young adults. "On the other hand, mitochondrial hyperfusion induced by knockdown of Drp1 or mitochondrial fission factor, delays cell cycle progression and promotes G2/M accumulation and caspase-dependent cell death in U2OS osteosarcoma cells." (PMID 26057632, 2015).
renal failure (1 paper, 2024). "Studies have shown that genetic deletion of MFF suppresses pro-inflammatory responses, renal tubular oxidative stress, and renal cell death, significantly mitigating renal failure caused by ischemic acute kidney injury (AKI)." (PMID 39916955, 2024).
rhabdomyosarcoma (1 paper, 2025). A rare aggressive malignant mesenchymal neoplasm arising from skeletal muscle. "In the rhabdomyosarcoma model, immunoblotting revealed up-regulation of the mitochondrial outer membrane adaptor proteins MFF and FIS1, which might contribute to alternative DRP1-independent mitochondrial fission." (PMID 39643272, 2025). "Similar compensatory mechanisms might also be adopted by sarcoma cells, as evidenced by the up-regulation of the DRP1 adaptor proteins MFF and FIS1 in DRP1-depleted rhabdomyosarcoma RD cells, further suggesting that therapies targeting DRP1 for sarcoma may be likely to fail." (PMID 39643272, 2025). "The minimal impact on sarcoma cell physiology, along with the up-regulation of fission adaptor proteins (MFF and FIS1) detected in rhabdomyosarcoma cells, suggests an alternative DRP1-independent mitochondrial fission mechanism that may efficiently compensate for the lack of DRP1 activity." (PMID 39643272, 2025).
Stroke (1 paper, 2019). Sudden impairment of blood flow to a part of the brain due to occlusion or rupture of an artery to the brain. "Losmapimod progressively suppressed dynamin-like protein 1(DLP1)/mitochondrial fission factor (MFF) from 6 h to 24 h after ischemia-reperfusion injury of rats, which suggested potential neuroprotective effect via suppressing mitochondrial fragmentation/mitophagy in stroke." (PMID 31547243, 2019).
ZIKV infection (1 paper, 2025). "Silencing of Bmal1 combined with ZIKV infection resulted in alternations of the expression of several mitochondrial proteins, including the pDRP1s616/DRP1 ratio, MFF, and OPA1 in brain endothelial cells." (PMID 40313764, 2025).
cancer (17 papers, 2017 to 2025). A tumor composed of atypical neoplastic, often pleomorphic cells that invade other tissues. "A study in cancer-associated myofibroblasts found that mitochondrial fission via overexpression of mitochondrial fission factor, an adaptor that facilitates fission, promotes glycolytic reprogramming and enhanced tumor growth." (PMID 28513539, 2017). "A mitochondrial fission factor, Drp1, has an oncogenic role in multiple cancers by promoting autophagy, altering energy metabolism pathways, and promoting cancer cell survival." (PMID 36831455, 2023). "Similarly, over-expression of another mitochondrial fission factor DRP1 has also been shown to promote tumor cell growth in human cancers of liver, lung and breast." (PMID 33317572, 2020). "In the cancer cell lines, expression of both MFN2 and DRP1 is significantly increased, while MFF expression is significantly lower in MDA-MB-231 cells compared to MCF7 cells." (PMID 39851508, 2025). "Mitochondrial fission factor (MFF), an important regulator of mitochondrial fission and function, tends to be highly expressed in cancer cells, and dysregulated mitochondrial fission has oncogenic effects." (PMID 40867281, 2025). "A number of these genes, including ACYP1, MFF, SLC44A1, and HFE, promote cancer development by regulating metabolic pathways." (PMID 40503897, 2025). "Several fission-inducing proteins, like mitochondrial fission factor (MFF), Dynamin-related protein-1 (DRP1), and mitochondrial dynamics proteins-49 (MiD49), are often expressed more in cancer cells than healthy counterparts." (PMID 37568652, 2023). "In addition, the mitochondrial fission factor (MFF) was identified as a transcriptional target of MYC, and was found to be overexpressed in cancer cells." (PMID 33494394, 2021). "To explore the hypothesis that dysregulated mitochondrial dynamics may impact drug sensitivity, we began by examining the alteration status of six canonical dynamics-regulating genes - OPA1, MFN1, MFN2, FIS1, MFF, and DNM1L (which encodes Drp1)—in human cancers." (PMID 29700304, 2018).
tumor (17 papers, 2012 to 2025). "Mitochondrial fission is a process commonly implicated in tumor progression, where dynamin-related protein-1 (Drp1) is bonded to one of its receptors, mitochondrial fission factor (MFF), on the mitochondrial outer membrane." (PMID 33498743, 2021). "MFF is upregulated in metastatic PCa and stem cell enriched tumor spheres compared with primary tumors and normal prostate tissue; moreover, MFF repression limits tumor growth by impairing asymmetric stem cell division with loss of self-renewal." (PMID 35269393, 2022). "Immunofluorescence analysis of the transplanted tumor cells using Ki-67 revealed that sh-FIS1 significantly suppressed tumor cell proliferation, whereas sh-MFF exhibited the opposite effect." (PMID 39350223, 2024). "MFF knockdown strongly inhibited the initiation and development of subcutaneous xenografts in nude mice, as reflected by their growth curves and tumor weights." (PMID 37291333, 2023). "First, we found that MFF knockdown attenuated the inhibition of the tumor burden induced by cisplatin." (PMID 25912308, 2015). "Here, we used MFF (mitochondrial fission factor) as a genetic tool to assess the metabolic effects of a “pre-fertilized” microenvironment on tumor growth and angiogenesis." (PMID 22878233, 2012). "Therefore, we conducted repeated interventions and related experiments in GSCs to investigate the impact of DNM1L/DRP1, FIS1 and MFF expression on tumor progression in different metabolic models." (PMID 39350223, 2024). "After knockdown of CPT1A or MFF, mitochondrial fusion is enhanced, and tumor cell growth is inhibited, partly because fused mitochondria might lead to the accumulation of damaged or senescent mitochondria in cells, which is not conducive to cell survival." (PMID 37291333, 2023). "However, following up-regulation of MFF, the expression levels of DNM1L/DRP1 and FIS1 were observed to decrease, thereby inhibiting tumor proliferation and progression." (PMID 39350223, 2024). "Although SLC25A5, ACSF2, MFF, and PMAIP1 have not been previously linked to PE, they are known to significantly influence mitochondrial function and tumor cell death." (PMID 39916955, 2024). "In contrast, overexpression of CISAL inhibited tumor growth and enhanced cisplatin sensitivity, whereas apoptotic tumor cells, CISAL, BRCA1, miR-593-5p, and MFF expression, were also detected, supporting the idea that enforced CISAL expression inhibits BRCA1 transcription in vivo." (PMID 32000125, 2020).
neurological disorders (3 papers, 2018 to 2021). "Interestingly, a subset of ASD-associated genes that were recovered after IGF-1 treatment has previously been linked to neurological disorders such as MFF, a mitochondrial gene that is associated with Leigh-like encephalopathy, and Nup93, a nucleoporin important in neuronal differentiation." (PMID 32591005, 2020). "The functional importance of both MFF and Drp1 in mitochondrial physiology has been demonstrated by the evidence that genetic mutations of MFF and DNM1L play causal roles in patients with developmental abnormalities and neurological disorders." (PMID 34745083, 2021).
infection (2 papers, 2022 to 2024). The state of being infected such as from the introduction of a foreign agent such as serum, vaccine, antigenic substance or organism. "In contrast, immunoreactive levels of FOXK2, OPA1, MFF, and PHB1 generally were preserved in the majority of Fbxo24+/− mice regardless of infection." (PMID 38735474, 2024).
neurodegenerative disease (2 papers, 2021 to 2022). A disorder of the central nervous system characterized by gradual and progressive loss of neural tissue and neurologic function. "The mitochondrial transcription factor A (TFAM) essential for genome maintenance, creatine kinase U-type (CKMT1) involved in energy metabolism, and mitochondrial fission factor (MFF) involved in the mitochondrial fission process are often decreased in neurodegenerative diseases including AD." (PMID 35269905, 2022).
peripheral neuropathy (1 paper, 2021). A disorder affecting the peripheral nervous system. "Meanwhile, other patients with truncating mutations in MFF have also been reported with similar phenotypes as well as peripheral neuropathy." (PMID 33810506, 2021). "Intriguingly, pathogenic variants in many of the peripheral neuropathy proteins discussed here lead to hyperfused mitochondrial networks (e.g., SLC25A46, DRP1, MFF, GDAP1, MYH14)." (PMID 33810506, 2021).
MFF also shares sentences with these, for which no sentence is quoted: liver cancer (3 papers); developmental delay (2); myelodysplastic syndrome (2); acute myeloid leukemia (1); Anxiety (1); Atrophy (1); brain tumor (1); cardiac hypertrophy (1); centronuclear myopathy 1 (1); colorectal cancer (1); diabetic cardiomyopathy (1); diabetic retinopathy (1); epilepsy (1); Epileptic encephalopathy (1); glioblastoma (1); Hearing impairment (1); heart disease (1); heart failure (1); Hyperglycemia (1); Infertility (1); Insulin resistance (1); Leigh syndrome (1); lung carcinoma (1); mitochondrial disease (1); mitochondrial encephalomyopathy (1); Myocardial fibrosis (1); myocardial ischemia (1); neuropathy (1); Non-alcoholic fatty liver disease (1); peroxisome biogenesis disorder (1).
A further 2 diseases each share a sentence with MFF in 1 paper.